EIF2S3 (eukaryotic translation initiation factor 2 subunit gamma)
Description:
Member of the eIF2 complex that functions in the early steps of protein synthesis by forming a ternary complex with GTP and initiator tRNA. This complex binds to a 40S ribosomal subunit, followed by mRNA binding to form the 43S pre-initiation complex (43S PIC) (By similarity). Junction of the 60S ribosomal subunit to form the 80S initiation complex is preceded by hydrolysis of the GTP bound to eIF2 and release of an eIF2-GDP binary complex (By similarity). In order for eIF2 to recycle and catalyze another round of initiation, the GDP bound to eIF2 must exchange with GTP by way of a reaction catalyzed by eIF-2B (By similarity).
Synonyms: eIF2gX; EIF2G; EIF2gamma; EIF2; MEHMO; MRXSBRK; eIF-2gA
Tractability: Small molecule: a structure with a bound ligand is known. PROTAC: ubiquitination databases record sites on it; its protein half-life has been measured.
Gene: Protein-coding gene on chromosome X (24,054,911 to 24,078,810, forward strand). Ensembl gene ENSG00000130741.
Subcellular location: Cytoplasm, cytosol
Pathways (Reactome):
Metabolism of proteins: Formation of the ternary complex, and subsequently, the 43S complex; GTP hydrolysis and joining of the 60S ribosomal subunit; L13a-mediated translational silencing of Ceruloplasmin expression; Recycling of eIF2:GDP; Ribosomal scanning and start codon recognition; Translation initiation complex formation
Cellular responses to stimuli: Cellular response to mitochondrial stress; PERK regulates gene expression; Response of EIF2AK1 (HRI) to heme deficiency; Response of EIF2AK4 (GCN2) to amino acid deficiency
Immune System: PKR-mediated signaling
Transport of small molecules: ABC-family protein mediated transport
Gene Ontology:
Molecular function: cadherin binding; protein binding; translation factor activity, RNA binding; translation initiation factor activity; GTPase activity; methionyl-initiator methionine tRNA binding; tRNA binding; GTP binding
Biological process: cytoplasmic translational initiation; translational initiation; formation of translation preinitiation complex; regulation of translational initiation
Cellular component: cytoplasm; eukaryotic translation initiation factor 2 complex; extracellular exosome; nucleus; cytosol
Gene-disease validity (ClinGen):
ClinGen rates the evidence that EIF2S3 causes each of these diseases.
MEHMO syndrome (X-linked): Definitive. MEHMO syndrome is characterized by severe intellectual deficit, epilepsy, microcephaly, hypogenitalism, and obesity.
Homologues: Orthologues: macaque EIF2S3 (99% identical), tropical clawed frog eif2s3 (97% identical), zebrafish eif2s3 (97% identical), Drosophila melanogaster eIF2gamma (81% identical), Caenorhabditis elegans eif-2gamma (73% identical), Caenorhabditis elegans tufm-2 (16% identical), Drosophila melanogaster mEFTu2 (16% identical). Paralogues in human: EIF2S3B (99% identical), EEF1A1 (26% identical), EEF1A2 (24% identical), TUFM (19% identical), GSPT1 (19% identical), GSPT2 (19% identical), HBS1L (19% identical), MTIF2 (17% identical), GFM1 (17% identical), EEFSEC (16% identical), EEF2 (16% identical), EFTUD2 (16% identical), and 6 more.
Diseases named in the same sentence as EIF2S3 in open-access papers:
EIF2S3 is named in the same sentence as 36 diseases in open-access papers, as found by Europe PMC text mining. Sharing a sentence is not in itself a finding about the gene and the disease. The quoted sentences say what the papers report.
microcephaly (10 papers, 2017 to 2023). A congenital or acquired developmental disorder in which the circumference of the head is smaller than normal for the person's age and sex. "Certain mutations in the gene for eIF2Bγ (EIF2S3) are associated with the disorder MEHMO (microcephaly, epileptic seizures, microcephaly, hypogenitalism, diabetes and obesity;56)." (PMID 37143925, 2023). "EIF2S3 has been linked to X linked mental retardation, hypogonadism, obesity, microcephaly and epilepsy and among its related pathways are regulation of lipid metabolism and insulin." (PMID 30213969, 2018). "Missense mutations in eIF2γ (encoded by EIF2S3) that disrupt eIF2 complex integrity have been identified in patients with X-linked microcephaly, epilepsy, and micropenis." (PMID 28951826, 2017). "EIF2S3 encoding a subunit of the eukaryotic translation initiation factor 2, eIF2γ, and hemizygous mutations have been associated with a more severe syndrome of developmental delay/intellectual disability, epilepsy, hypogonadism, microcephaly, and obesity (MEHMO syndrome, OMIM #300148)." (PMID 37065762, 2023). "Mutations in EIF2S3 cause MEHMO, a rare X-linked syndrome characterized by intellectual disability, epilepsy, hypogonadism, hypogenitalism, microcephaly, and obesity." (PMID 37085889, 2023). "We describe two brothers with a recurrent truncating EIF2S3 variant and MEHMO (Mental retardation, Epileptic seizures, Hypogonadism and ‐genitalism, Microcephaly, Obesity)." (PMID 35765291, 2022). "A recent study identified EIF2S3 mutations in patients with MEHMO syndrome (mental retardation, epilepsy, hypogonadism and -genitalism, microcephaly, and obesity)." (PMID 28951826, 2017). "Notably, mutations in the human EIF2S3 result in the brain affecting MEHMO syndrome (Mental retardation, Epileptic seizures, Hypogenitalism, Microcephaly, and Obesity) in males." (PMID 37176068, 2023). "Indeed, mutations in EIF2S3, the gene encoding eIF2γ that was shown to compromise eIF2 complex integrity and translation initiation, cause MEHMO (#MIM300148), a syndrome associating epilepsy, hypogonadism, obesity and microcephaly with ID." (PMID 31832602, 2019).
MEHMO syndrome (7 papers, 2021 to 2024). "Mutations in EIF2S3 have been associated with severe neurological diseases including MEHMO syndrome." (PMID 39153206, 2024). "MEHMO syndrome is caused by mutations in EIF2S3 and can be inherited from an unaffected mother or arise de novo." (PMID 35765291, 2022). "Mutations in EIF2S3 have been linked to MEHMO syndrome development, an X-linked intellectual disability disorder." (PMID 34281203, 2021).
hypopituitarism (4 papers, 2022 to 2023). A condition of diminution or cessation of secretion of one or more hormones from the anterior pituitary gland. "Recent description of loss of function mutations in EIF2S3, discovered by exome sequencing of the X-chromosome, were also been associated to hypoglycemia, hypopituitarism and pancreatic dysfunction in three boys." (PMID 35422763, 2022). "Three males from one family with a variant in EIF2S3 were reported with an unusual dysregulation of glucose fluctuating between diazoxide-responsive HH and postprandial hyperglycemia diagnosed in childhood, along with learning difficulties and hypopituitarism." (PMID 37065762, 2023). "EIF2S3 may play a critical role in human hypothalamo-pituitary development and function and regulation of glucose metabolism, and mutations in the EIF2S3 gene may contribute to neonatal hypoglycemia, followed by early onset diabetes and hypopituitarism." (PMID 37569434, 2023).
cognitive deficits (2 papers, 2020 to 2025). "EIF2S3 plays a direct role in synaptic plasticity and cognitive impairment, as well as in EIF2-controlled thermal nociceptive responses." (PMID 33183347, 2020). "Normally, XCI balances gene dosage, but in KS, genes such as GTPBP6 (guanosine triphosphate binding protein 6), EIF2S3 (eukaryotic translation initiation factor 2 subunit 3), and KDM5C (Lysine(K)‐specific demethylase 5C) escape inactivation and are overexpressed, contributing to cognitive deficits." (PMID 40018421, 2025).
colorectal cancer (2 papers, 2021 to 2023). A primary or metastatic malignant neoplasm that affects the colon or rectum. "Our results for EIF2S3 expression in colorectal cancer-derived cells are in accordance with findings in acute myeloid leukemia." (PMID 36672653, 2023). "According to the data obtained in our study, the increase in EIF2S3 mRNA level in peripheral blood samples stands out in colorectal cancer cases and our data contributes to these limited studies." (PMID 33237662, 2021). "Further study is therefore required to understand EIF2S3 mRNA changes in peripheral blood samples of colorectal cancer patients." (PMID 33237662, 2021). "Overall, DUSP6, MDM2, and EIF2S3 were consistently selected as significant factors associated with colorectal cancer in all logistic models and were not modulated by any other genes or clusters." (PMID 36672653, 2023). "The mRNA levels of CPEB4, APC, TRIP13, EIF2S3, EIF4A1, IFNg, PIK3CA and CTNNB1 genes expressed in colorectal cancer tissue specimens, colorectal cancer blood samples, normal colon tissues and blood samples were analysed." (PMID 33237662, 2021). "Considering the results related to EIF2S3 and EIF4A1 mRNA changes in the patients with colorectal cancer, the increase in mRNA levels in peripheral blood samples is remarkable." (PMID 33237662, 2021). "The aim of the study is to assess expression levels of CPEB4, APC, TRIP13, EIF2S3, EIF4A1, IFNg, PIK3CA and CTNNB1 genes in tumors and peripheral bloods of colorectal cancer patients in stages I–IV." (PMID 33237662, 2021). "In addition to this evaluation, although there is not much study on EIF2S3 and EIF4A1 mRNA changes in cases with colorectal cancer, upregulation in peripheral blood draws attention in our study." (PMID 33237662, 2021).
Cerebral ischemia (1 paper, 2025). Restriction of arterial blood supply to the brain associated with insufficient oxygenation to support the metabolic requirements of the tissue. "Results showed that only the sex difference of EIF2S3 was profoundly affected by cerebral ischemia in whole blood, rather than in monocytes and neutrophil." (PMID 40191607, 2025).
colorectal tumor (1 paper, 2021). "In our study, EIF2S3 mRNA levels increased in both colorectal tumor tissues and peripheral blood samples compared to the control group." (PMID 33237662, 2021).
ischemic stroke (1 paper, 2025). A stroke disorder caused by obstruction of blood flow to the brain, due to thrombotic (local blood clot formation) or embolic (due to a blood clot or other material traveling from another site) event. "Therefore, we explored whether KDM5C, KDM6A, or EIF2S3 displayed age-dependent expression changes in males and females and whether such age-dependent expression changes could be altered by ischemic stroke." (PMID 40191607, 2025).
Klinefelter syndrome (1 paper, 2021). A sex chromosome disorder caused by the presence of an extra X chromosome in the male karyotype. "Indeed, Klinefelter Syndrome patients have been reported to have an increased risk of ASDs; and our results suggest that an increased expression of EIF2S3 may at least partially contribute to this." (PMID 34307355, 2021).
lung carcinoma (1 paper, 2016). "EIF2S3 gene expression was a significant protector in the model for younger men, with the odds of having lung cancer decreasing by 79%." (PMID 27418131, 2016). "Each unit increase in the relative expression of the EIF2S3, POLDIP2, and RNF4 genes showed protective effects, with odds of having lung cancer decreased by 78%, 84%, and 78%, respectively." (PMID 27418131, 2016).
lymph node metastasis (1 paper, 2022). "Therefore, we used the clinical data and expression profile of TCGA-LUAD to analyze the association between the expression of NCAPG2 and EIF2S3, the clinical stage, and lymph node metastasis." (PMID 36139554, 2022). "Univariate regression analysis showed that EIF2S3, NCAPG2, the pathological stage, and lymph node metastasis were associated with the prognosis of LUAD patients." (PMID 36139554, 2022).
Stroke (1 paper, 2025). Sudden impairment of blood flow to a part of the brain due to occlusion or rupture of an artery to the brain. "Interestingly, EIF2S3 level was comparable between sexes in the whole blood of healthy cohort, but become significantly higher in females after stroke." (PMID 40191607, 2025). "Given XCI toward one parental X is skewed by sex and aging observed in multiple tissues, organs and cell types under either health or disease conditions, we assume that EIF2S3 might modulate the consequence after stroke through intertwined role of mechanisms." (PMID 40191607, 2025).
Syndromic (1 paper, 2023). "Syndromic disorders associated with impaired glucose metabolism and early-onset diabetes may manifest with CHI in early infancy as a common pattern (HNF4A, HNF1A microdeletion, EIF2S3)." (PMID 37065762, 2023).
X-linked intellectual disability syndrome (1 paper, 2024). "Another example is the X-linked intellectual disability syndrome, MEHMO, caused by missense mutations in the eIF2S3 gene encoding the eIF2γ subunit." (PMID 38462161, 2024).
tumor (4 papers, 2019 to 2022). "EIF2S1, EIF2S2, and EIF2S3 were all reported to associate tumor progression." (PMID 31258820, 2019). "Among all the genes reported in the literature with their potential cause in tumor development, CPEB4, APC, TRIP13, EIF2S3, EIF4A1, IFNg, PIK3CA and CTNNB1 have particularly been identified to be a set of potential candidates for tumor development." (PMID 33237662, 2021). "Based on previous research, we conjecture that tumor immune escape mediated by NCAPG2 and EIF2S3 may be involved in LUAD erlotinib resistance and stemness." (PMID 36139554, 2022). "EIF2S3 also increased with the tumor stage and lymph node invasion, but there was no significant change in distal metastasis." (PMID 36139554, 2022).
EIF2S3 also shares sentences with these, for which no sentence is quoted: cancer (6 papers); epilepsy (6); Obesity (6); hypogonadism (5); Intellectual disability (4); neurological disease (3); diabetes (2); Hypoglycemia (2); acute myeloid leukemia (1); cyst (1); developmental delay (1); head and neck squamous cell carcinoma (1); Hypercholesterolemia (1); Hyperglycemia (1); Hypertension (1); lung adenocarcinoma (1); Micropenis (1); ovarian carcinoma (1); ovarian tumours (1); testicular germ cell tumor (1); X-linked intellectual disability (1).